LENG8 (leukocyte receptor cluster member 8)
Synonyms: KIAA1932; MGC40108; pp13842
Tractability: PROTAC: ubiquitination databases record sites on it; its protein half-life has been measured.
Gene: Protein-coding gene on chromosome 19 (54,449,157 to 54,462,022, forward strand). Ensembl gene ENSG00000167615.
Subcellular location (Human Protein Atlas): Nucleoplasm; Cytosol
Gene Ontology:
Molecular function: protein binding
Cellular component: protein-containing complex
Genetic constraint (gnomAD): Loss-of-function variants: 28 observed, 102.32 expected, observed/expected ratio (o/e) 0.27, 90% interval 0.2 to 0.38. The upper end of that interval is the gene's LOEUF score, 0.38, which puts it in group 1 of 6, group 1 being the genes least tolerant of losing a copy. Missense variants: 1,022 observed, 1,121.7 expected, observed/expected ratio (o/e) 0.91, 90% interval 0.87 to 0.96. Synonymous variants: 531 observed, 458.55 expected, observed/expected ratio (o/e) 1.16, 90% interval 1.08 to 1.24.
Homologues: Orthologues: pig LENG8 (96% identical), guinea pig LENG8 (95% identical), chimpanzee LENG8 (94% identical), mouse Leng8 (93% identical), macaque LENG8 (93% identical), dog LENG8 (90% identical), rat Leng8 (88% identical), rabbit LENG8 (87% identical), tropical clawed frog leng8 (63% identical), zebrafish leng8 (52% identical), Caenorhabditis elegans hpo-10 (27% identical). Paralogues in human: MCM3AP (19% identical), SAC3D1 (8% identical).
Diseases named in the same sentence as LENG8 in open-access papers:
LENG8 is named in the same sentence as 7 diseases in open-access papers, as found by Europe PMC text mining. Sharing a sentence is not in itself a finding about the gene and the disease. The quoted sentences say what the papers report.
breast carcinoma (1 paper, 2019). "Differential expression of LENG8 in breast cancer has been confirmed." (PMID 31140607, 2019).
diabetes (1 paper, 2023). "Additionally, HSD11B1 and HLA-DRA linked hypertension, diabetes, and obesity; UCHL1 linked hypertension, obesity, and lung cancer; LENG8 and HSPA1L linked diabetes, obesity, and lung cancer." (PMID 36685671, 2023).
periodontitis (1 paper, 2024). An acute or chronic inflammatory process that affects the tissues that surround and support the teeth. "The allele frequencies at the mutation loci of LFNG, LENG8, NPHS1, HFE, ILDR1, and DMXL2 genes were analyzed in the 15 patients with severe periodontitis." (PMID 37435641, 2024).
tumor (4 papers, 2019 to 2025). "Some CSC marker genes showed extremely disparate expression levels between normal and tumor samples, such as PLCG2, DDX11, IER5L, LENG8, HAGHL and CPNE7." (PMID 37377935, 2023). "The common prognostic genes between AS event and genes included KRT222, LENG8, APOB, SLC3A1, SCD5, AQP1, and ADRA1A, which played roles in tumor biology." (PMID 31140607, 2019).
LENG8 also shares sentences with these, for which no sentence is quoted: Hypertension (1 paper); lung carcinoma (1); Obesity (1).